EGFR (epidermal growth factor receptor)
Diseases named in the same sentence as EGFR in open-access papers (continued):
Sharing a sentence is not in itself a finding about the gene and the disease.
cancer (continued). "Because EGFR activation often plays important role in cancers, many teams used various inhibitor agents, microarray platforms and experimental approaches in transcriptional studies of EGFR inhibition." (PMID 25184905, 2014). "This is a rationale for the development of EGFR interferent as antitumor agents in the cancer therapy." (PMID 25438047, 2014). "Afatinib is an orally, irreversible EGFR, HER2 and HER4 inhibitor, showing preclinical activity against cancer cells harboring common activating EGFR mutations and the T790M mutation, albeit with a lower potency." (PMID 25505694, 2014). "Gefitinib, an epidermal growth factor receptor (EGFR) type 1 tyrosine kinase inhibitor, blocks the signal transduction pathway implicated in the proliferation and survival of cancer cells." (PMID 24669240, 2014). "The mAb targeting of either EGFR or ERBB2 also generates an increased rate of apoptosis in cancer cells in vitro." (PMID 24970817, 2014). "EGF-containing fibulin-like extracellular matrix protein 1 (EFEMP1) is a secreted protein that was determined to inhibit cancerous glioma growth through the reduction of EGFR levels and intracellular AKT phosphorylation." (PMID 26056585, 2014). "This regulation of HER receptors sustains the growth of cancer cells after the EGFR blockade, and HER3 plays a central role in mediating such resistance to EGFR inhibition." (PMID 25400118, 2014). "The epidermal growth factor receptor (EGFR) plays an important role in response of cancer cells to therapy." (PMID 25401399, 2014). "Although such studies have largely focused on mitogenic signaling and dysregulated traffic in tumorigenesis, there is growing interest in the potential role of EGFR traffic in cell survival and the consequent response to cancer therapy." (PMID 24295852, 2014). "Thirty years ago mutant forms of EGFR and HER2 were linked to cancer cells in chicken and rat, respectively." (PMID 25520666, 2014). "Gene amplification in cancer cells provides a means for overexpression of cancer-promoting driver genes, such as EGFR and ERBB2 on chromosomes 7 and 17, respectively." (PMID 24874471, 2014). "Based on cBio cancer genomics portal, H4 cell line has PTEN homozygous deletion and EGFR amplification; NCI-H1975 and CAOV-3 both have a PIK3CA mutation and an EGFR mutation." (PMID 25361177, 2014). "Sym004, the mixture of two monoclonal anti-EGFR antibodies, induced removal of the receptor from the cancer cell surface by triggering EGFR internalization and degradation, and was effective in treatment of Cetuximab-resistant tumors." (PMID 25520666, 2014). "Here, we have studied the intracellular dynamics of PTPD1, a FERM (four-point-one, ezrin, radixin, moesin) domain-containing PTP that is over expressed in cancer cells and potentiates EGFR signalling." (PMID 25062045, 2014). "S2RPGRMC1 inhibitors are attractive in this setting because they inhibit EGFR-dependent cancer cell proliferation and are most active against the wild-type form of the protein." (PMID 25594057, 2014). "The activation of EGFR is prevalent in cancer signaling and not only activates PI3K by recruiting the regulatory subunit, p85, but also induces activation of the mitogen-activated protein kinase (MAPK) pathway by either Grb2 or Shc adaptor proteins." (PMID 25053989, 2014). "Lab-on-chip and optical biosensors have been used for detection of epidermal growth factor receptor (EGFR) biomarker for early diagnosis of cancer." (PMID 25165697, 2014). "YAP depletion further sensitizes human cancer cells to anti-cancer agents, such as cisplatin or the EGFR tyrosine kinase inhibitor erlotinib, and increased YAP/TAZ levels correlate with taxol and cisplatin resistance." (PMID 25097725, 2014). "While this connection uncovers new avenues for neuroprotection, it also provides a plausible mechanistic basis for the correlative actions of platelets, EGFR and DNA-PK during cancer." (PMID 25210793, 2014).
cancer (continued). "The discovery some years later that EGFR had tyrosine kinase activity was an upheaval in growth factor and cancer biology." (PMID 24709958, 2014). "The cross-talk between constitutively active EGFR- and NF-κB-dependent pathways in cancer is poorly understood." (PMID 25366117, 2014). "A single somatic mutation in ACK1 that abrogates ubiquitin binding can stabilize the EGFR at the plasma membrane, thereby prolonging mitogenic signaling after EGF stimulation and making some cancers resistant to EGFR kinase inhibitors such as gefitinib." (PMID 24295852, 2014). "These TKIs are aimed at the existing EGFR mutation in NSCLC cells, inhibit the tyrosine kinase activity of EGFR thus to suppress the growth of the cancer cells." (PMID 24625581, 2014). "To further extend our findings to specimens obtained from human cancer patients, we evaluated the expression of both p27Kip1 and EGFR in human cancer specimens using IHC staining." (PMID 25121353, 2014). "There was a statistically significant difference in the EGFR gene copy number alterations between the benign and malignant tumors (P < 0.001)." (PMID 24457059, 2014). "Inhibiting IL-6/JAK/STAT3 signaling or STAT3 activity alone with antisense oligonucleotides, siRNA, or small-molecule inhibitors can dramatically sensitize cancer cells to treatment with EGFR inhibitors." (PMID 24662938, 2014). "Further, proximity ligation assay (PLA) revealed colocalization of CXCR7 with EGFR in cancer tissues and cancer cell lines." (PMID 25168820, 2014). "In particular, we characterize global features of functional dynamics for members of the EGFR, CDK, NEK, BTK, and ITK kinases that have various cancer mutations." (PMID 24817905, 2014). "Using the cBIO Cancer Genomic Portal, we confirmed the well-established enrichment of relatively increased EGFR mRNA in BBC [RNAseq z-score > 1 in 14/81 (28%) of BBC versus 6/324 (2%) of luminal cases." (PMID 25361177, 2014). "Since its discovery, the epidermal growth factor receptor (EGFR) continues to be the subject of myriad investigations in cancer signalling." (PMID 25389535, 2014). "We envision that low dose UVB light can be used as a new photonic therapeutical approach used in order to stop the development of localized cancer, which cells overexpress EGFR or another receptor which structure will be labile to UV light." (PMID 25386651, 2014). "We have identified two classes of compounds that exhibit preferential cytotoxicity against cancer cells over normal cells when cultured as 3D spheroids: microtubule-targeting agents and epidermal growth factor receptor (EGFR) inhibitors." (PMID 25247711, 2014). "While several therapeutic agents against erbB2 and/or EGFR have been used in the treatment of human cancers with efficacy, there has been relatively less emphasis on erbB3 as a molecular target." (PMID 24886126, 2014). "The microRNA, miR-7 has been shown to antagonize EGFR expression, to be involved in EGFR-related cancer progression, and to regulate EGFR-mediated development." (PMID 24134702, 2014). "In fact, we detected synergistic cell death from three other cancer lines H4, CAOV-3 and NCI-H1975, which harbor either PTEN or PI3KCA mutation and EGFR amplification or mutation." (PMID 25361177, 2014). "More than half of the genes identified in our previous study of gene regulation by EGFR blockade were significantly modulated upon ErbB2 inhibition in ErbB2-positive cancer cells as well suggesting highly shared oncogenic pathways." (PMID 25238247, 2014). "From this point of view, skin disorder with inhibitors of the EGFR system can be used to continue the drug administration for cancer therapy, which is most important simultaneous with symptom control of the skin disorder." (PMID 24517087, 2014). "Our results suggest that B4GALNT3 plays a role in regulating cancer stem like cell property via the EGF/EGFR pathway." (PMID 25003232, 2014).
cancer (continued). "We discovered that there was a statistically significant difference between benign and malignant tumors regarding their alterations in the EGFR gene copy number." (PMID 24457059, 2014). "MicroRNA-7 (miR-7) has been reported to target and prevent EGFR production in many instances such as in cancers and during development." (PMID 24134702, 2014). "Inhibition of the activated epidermal growth factor receptor (EGFR) with either enzymatic kinase inhibitors or anti-EGFR antibodies such as cetuximab, is an effective modality of treatment for multiple human cancers." (PMID 24894453, 2014). "We correlated drug activities to cancer gene mutations and identified new drug sensitivity markers for MEK and EGFR inhibitors." (PMID 24651269, 2014). "In detail, overexpression of NEU3 gives rise to activation of EGFR-downstream signaling, which in turn brings to survival of different human cancer cells." (PMID 24925219, 2014). "Abnormal signaling by the epidermal growth factor receptor (EGFR) contributes to the development of various human diseases, including different cancer types." (PMID 24785082, 2014). "Abnormally high levels of the EGFR protein are frequently found on the surface of many types of cancer cells, facilitating the excessive cell division that is the hallmark of cancer." (PMID 24550933, 2014). "Phosphorylated EGFR (pEGFR) immunoreactivity was observed in the cytoplasm and nuclei of cancer cells, whereas the pattern of EGFR staining was membranous and cytoplasmic." (PMID 25416285, 2014). "In humans, EGFR also localizes to the basolateral membrane of epithelial cells, and excessive EGFR signaling is a major driver of cancer." (PMID 25329472, 2014). "The epidermal growth factor receptor (EGFR) has evolved over years into a main molecular target for the treatment of different cancer entities." (PMID 24603603, 2014). "Since the activation of EGFR is playing major role in the metastasis of many cancers, we also detected its phosphorylation status after miR-7 transfection in HO-8910pm and ES-2 cells." (PMID 24816687, 2014). "A previous study reported that the effects of EGFL7 are mediated by the EGFR signaling pathway, which is critical for controlling cancer cell motility." (PMID 24945379, 2014). "Although EGFR inhibitors have been widely used to treat many types of cancer, the usefulness of these therapies is limited due to the appearance of drug resistance." (PMID 25240937, 2014). "Molecular signaling pathways of growth factor receptors, such as the Epidermal Growth Factor (EGF) Receptor (EGFR), stimulate cancer cell growth, survival and resistance to cytotoxic therapy." (PMID 24456610, 2014). "It is also noteworthy that, compared to ASCs-CM, hUCESCs-CM contain lower levels of factors known to participate in cancer progression, such as EGFR, FGF 4 and 9, ICAM3, IL6, IL6R, MCP3 (CCL7), MIF, sgp130 and VEGFD." (PMID 25296979, 2014). "Evolving from several decades of systematic research in cancer cell biology, several EGFR inhibitors, such as monoclonal antibodies and tyrosine kinase inhibitors have been developed and implemented in clinical application." (PMID 25216514, 2014). "Cancer cell target: Epidermal growth factor receptor monoclonal antibody, epidermal growth factor, human epidermal receptor 2, transferrin, A10 aptamer, As1411 aptamer, cRGD, galactose, hyaluronic acid, folic acid, glycyrrhizin, etc." (PMID 25522316, 2014). "Given the elevated expression and genomic alterations present in EGFR, multiple cancer therapies have targeted EGFR, as both its kinase activity and its dependence on extracellular ligand signaling have rendered EGFR vulnerable to therapeutic intervention." (PMID 24894453, 2014). "The upregulation of fibroblast growth factor 17 (FGF17) and epidermal growth factor receptor (EGFR) by genistein clearly indicated the stimulation of different signaling pathways which have been known to be involved in cancer." (PMID 24967385, 2014).
cancer (continued). "Deregulation of signaling through the human epidermal growth factor receptor (HER; also known as ERBB) family of proteins has an intricate role in the pathogenesis of numerous human cancers." (PMID 25025184, 2014). "In summary, our studies define putative and novel resistance mechanisms to lapatinib in ErbB2-positive cancers and identify irreversible EGFR/ErbB2 inhibitors as capable of overcoming such resistance." (PMID 25238247, 2014). "It has become increasingly evident that the crosstalk between PAFR and EGFR confer an aggressive tumorigenic phenotype in cancer cells." (PMID 25261977, 2014). "Drugs that inhibit proteins central to cancer growth or DNA repair, such as the EGFR inhibitor cetuximab, can impede DNA repair and make cancer more susceptible to radiation." (PMID 25344917, 2014). "For example, epidermal growth factor receptor (EGFR) has been reported to be overexpressed in many cancer cells including ESCC." (PMID 24797725, 2014). "There was a statistically significant difference in the EGFR immunostaining between benign and malignant tumors (P = 0.035)." (PMID 24457059, 2014). "Epidermal growth factor receptor (EGFR) is a cell surface growth factor receptor kinase that has been involved in different types of cancers." (PMID 24992720, 2014). "For our experiments we used the HeLa cell line, which has been reported to express high levels of endogenous EGFR and is therefore frequently used in cancer research." (PMID 24658383, 2014). "Amplification and over-expression of EGFR and HER2 have been described in PCa and associated with cancer progression, poor prognosis or development of androgen independence." (PMID 24516518, 2014). "Since a series of EGFR inhibitors such as gefitinib, erlotinib, lapatinib and vandetanib were approved for cancer therapy, and thus the 4-aminoquinazoline skeleton has been considered a promising nucleus for antitumor drug development." (PMID 25551444, 2014). "Further intensive research efforts have been focused on clarifying the mechanisms by which cancer cells acquire resistance to EGFR-targeted drugs." (PMID 25115383, 2014). "What is worse, in some cases, is that radiation actually increases the expression of cancer-promoting genes, such as EGFR, resulting in radiation resistance." (PMID 25344917, 2014). "Earlier studies had implicated a role for PI3K/Akt, epidermal growth factor receptor (EGFR) activation, and Bcl-2 in the survival of cancer cells under detachment." (PMID 25096718, 2014). "ERBB2 is a member of the epidermal growth factor receptor (EGFR/ErbB) family, and usually over expressed in many kind of cancer cells and promoting cell proliferation." (PMID 25479352, 2014). "In cancer cells, EGFR signaling is often enhanced due to overexpression of ligands, the elevated level of the receptor, and the presence of activating mutations." (PMID 25401399, 2014). "This will open up the prospect of development of future treatment strategies, including the targeting of factors involved in the regulation of cancer therapy-induced EGFR endocytosis and subsequent intracellular traffic." (PMID 24295852, 2014). "EGFR appears to be one of the most promising and effective targets in the treatment of head and neck and breast cancer." (PMID 25120710, 2014). "EGFR monoclonal antibodies and EGFR tyrosine kinase inhibitors have been approved for use in cancer patients." (PMID 24886678, 2014). "This is distinct from protein anti-cancer drugs like gefitinib that target protein receptors (e.g. epidermal growth factor receptor)." (PMID 25310698, 2014). "Cancer membrane-associated proteins have been targeted to develop cancer therapeutics, such as herceptin (her2neu), Panorex (Ep-CAM) and IRESSA (epidermal growth factor receptor)." (PMID 25299694, 2014).
cancer (continued). "To provide direct evidence that p27Kip1-regulated EGFR expression via the JNK/c-Jun axis plays a role in cancer cell growth, we infected T24T cells with an adenovirus-driven-GFP–p27Kip1 and adenovirus-driven GFP as a negative control." (PMID 25121353, 2014). "Another aspect of the regulation of EGFR trafficking that is likely to play a key role in cancer development and patient outcome is the effect of current cancer therapies on EGFR traffic." (PMID 24295852, 2014). "Another small network including EGFR (four isoforms) and two other well-established cancer related genes viz." (PMID 25034693, 2014). "SHIP2 also promotes cancer cell proliferation and metastasis by preventing epidermal growth factor receptor (EGFR) turnover and enhancing EGF-induced Akt activation." (PMID 25525286, 2014). "EGFR is overexpressed in PCa and plays an important role in cancer cell growth, especially during androgen withdrawal." (PMID 24797896, 2014). "It is interesting that a novel drug HM90822B showed cell growth-inhibitory effect on NSCLC cells, especially on IAP and EGFR-overexpressing cells, because both molecules are regarded as oncogenic and tumorigenic in different types of cancers." (PMID 25321484, 2014). "Despite their highly promising activity of EGFR inhibitors for cancer treatment, there is a large group of CRC patients that do not respond to anti-EGFR therapy." (PMID 25301722, 2014). "Nanobodies against EGFR developed in our group have shown several advantages in cancer detection when compared to mAbs." (PMID 25520666, 2014). "Numerous studies have reported the activation of EGFR as a resistance mechanism to various anti-cancer therapies." (PMID 25004126, 2014). "Multiple reports have described miR-7 as having an important role in the regulation of EGFR in cancer and development." (PMID 24134702, 2014). "EGFR autocrine/paracrine pathways contribute to a number of processes that are important in the development and progression of cancer, including cell proliferation, apoptosis, angiogenesis, and metastatic spread." (PMID 24433534, 2014). "Previous studies have revealed that aberrant N-glycosylation of integrin, EGFR, and N-cadherin modified by GnT-V, resulted in alteration of signal pathways, all contributing to cancer progression." (PMID 24846175, 2014). "Targeting epidermal growth factor receptor (EGFR) has been intensively pursued as a cancer strategy." (PMID 25032217, 2014). "Unfortunately, cancers become resistant to many types of therapies that specifically target EGFR, HER2, or components of their downstream pathways." (PMID 25566499, 2014). "If observed, this will give us insight into why UVB illumination (280 nm) of cancer cells overexpressing EGFR led to the arrest of the EGFR signaling pathway." (PMID 25386651, 2014). "Researchers have continued to elucidate crosstalk between Notch and EGFR in hopes to dissect the mechanism(s) by which this crosstalk occurs and to better comprehend how cancer cells use the Notch pathway to compensate for EGFR targeted inhibition." (PMID 25566499, 2014). "Epidermal growth factor receptor (EGFR; ErbB1) is a member of the ErbB family of receptor tyrosine kinases that plays an integral role in the oncogenesis of several ErbB-driven cancers, including HNSCC." (PMID 24973959, 2014). "So far, few studies have evaluated overexpression of EGFR ingallbladder carcinoma cases, and the rates of positive findings fromimmunohistochemistry have ranged from 16 to 100%4,6,8,13,15,21,26." (PMID 25004291, 2014). "Gemcitabine has been covalent bonded to a number of biologically relevant ligands with binding avidity for trophic receptors like HER2/neu and EGFR that are frequently over-expressed by many carcinomas and adenocarcinomas including those affecting the breast." (PMID 25844392, 2014). "But approximately 70% of metaplastic carcinomas show epidermal growth factor receptor (EGFR) gene amplification and overexpression." (PMID 24625319, 2014).